ITGA8 (integrin subunit alpha 8)
Diseases named in the same sentence as ITGA8 in open-access papers (continued):
Sharing a sentence is not in itself a finding about the gene and the disease.
lung carcinoma (2 papers, 2023 to 2024). "In our study, initial exploration of the function of ITGA8 in lung cancer was performed through bioinformatics analysis." (PMID 36911684, 2023). "The examination of public databases revealed that ITGA8 expression was significantly lower in tumor tissue than that in normal tissue, especially in lung cancer, renal carcinoma, and prostate cancer." (PMID 36911684, 2023). "We determined regulatory genes upstream through an online database to explore the regulatory role of ITGA8 in lung cancer." (PMID 36911684, 2023). "Finally, the gene regulatory network of ITGA8 constructed through bioinformatics analysis, can help to explore the molecular mechanism of lung cancer and discover novel therapeutic targets." (PMID 36911684, 2023). "If ITGA8 is used as a biomarker for lung cancer diagnosis, treatment, and prognosis in the future, the expression of these genes may support it." (PMID 36911684, 2023). "Studies on the relationship between ITGA8 and lung cancer are scarce and therefore, warranted." (PMID 36911684, 2023). "Therefore, the regulatory network of ITGA8 may serve as a new therapeutic target to improve the prognosis of patients with lung cancer." (PMID 36911684, 2023). "However, the functional role of ITGA8 in lung cancer has not been characterized." (PMID 36911684, 2023).
multiple myeloma (2 papers, 2020). "A study found that ITGA8 is highly expressed in early recurring myeloma and can be used as a potential marker of multiple myeloma recurrence." (PMID 33335550, 2020). "The gene ITGA8, among other studies, was studied in multiple myeloma cell lines since it was discovered its high expression in patients with early relapse." (PMID 32784482, 2020). "These, consequently, enhanced migration and invasion abilities, which are crucial to multiple myeloma pathogenesis; this evidence could be transposed into the hADSC model where ITGA8 could be seen as a factor promoting stemness." (PMID 32784482, 2020).
pancreatic cancer (2 papers, 2023 to 2025). "To further investigate the functional dependency of RAGE and ITGA8, we used the pancreatic cancer cell line, MIA PaCa-2." (PMID 41294858, 2025). "We investigated ITGA8 levels following RAGE knockdown in RAGE-expressing HEK293 cells and the pancreatic cancer cell line Mia PaCa2-2, which is reported to express endogenous RAGE." (PMID 41294858, 2025). "According to our understanding, no previous studies have explored whether IKZF3 and ITGA8 are engaged in the initiation and progression of pancreatic cancer." (PMID 36837559, 2023).
Parkinson disease (2 papers, 2016 to 2025). A progressive degenerative disorder of the central nervous system characterized by loss of dopamine producing neurons in the substantia nigra and the presence of Lewy bodies in the substantia nigra and locus coeruleus. "Moreover, the ability of ITGA8 to modulate pericyte function may also extend to other neurological conditions involving BBB impairment, such as Parkinson's disease." (PMID 41085070, 2025).
abdominal aortic aneurysm (1 paper, 2023). Enlargement and ballooning of the vessel that supplies arterial blood to the abdomen, pelvis and legs. "In conclusion, Itga8-Cre deletion of YAP and TAZ represents a rapid and spontaneous aneurysm model that recapitulates features of human abdominal aortic aneurysms." (PMID 37561588, 2023).
Alzheimer disease (1 paper, 2025). A progressive, neurodegenerative disease characterized by loss of function and death of nerve cells in several areas of the brain leading to loss of cognitive function such as memory and language. "This study reveals the critical role of ITGA8 in maintaining BBB integrity and promoting pericyte‐mediated vascular maturation, offering new therapeutic insights for neurodegenerative disorders such as Alzheimer's disease (AD) and multiple sclerosis (MS)." (PMID 41085070, 2025).
aneurysm (1 paper, 2023). Bulging or ballooning in an area of an artery secondary to arterial wall weakening. "In order to understand whether this pathway protects from aneurysm development, 6- to 8-week-old Yap1fl/fl × Wwtr1fl/fl mice with 1 allele of the Itga8-CreERT2 transgene were injected intraperitoneally with tamoxifen for inducible KO of YAP and TAZ in vascular smooth muscle (i8-YT-KO)." (PMID 37561588, 2023).
clear cell renal cell carcinoma (1 paper, 2020). "ITGA8 can also be used to predict the prognosis of clear cell renal cell carcinoma." (PMID 33335550, 2020).
Fraser syndrome (1 paper, 2017). Fraser syndrome is a rare clinical entity including as main characteristics cryptophthalmos and syndactyly. "Of the candidate genes, four genes (i.e., ITGA8, GRIP1, FREM1, and FREM2) were Fraser syndrome-related genes, encoding proteins that functionally converged on the glial cell-derived neurotrophic factor/RET/bone morphogenic protein (BMP) signaling pathways." (PMID 29197384, 2017).
glomerulosclerosis (1 paper, 2017). A hardening of the kidney glomerulus caused by scarring of the blood vessels. "Male Apoe−/− mice with the additional deficiency of Itga8 developed increased serum urea, glomerulosclerosis, renal immune cell infiltration, and reduced glomerular cell proliferation." (PMID 28572914, 2017). "Moreover, Itga8 deficiency (Itga8−/−) resulted in more pronounced glomerulosclerosis and increased cortical collagen I expression in Apoe-deficient (Apoe−/−) males as compared to females." (PMID 28572914, 2017). "As a consequence, mice with a deletion of Itga8 do not develop overt glomerular injury per se, but are prone to develop glomerulosclerosis when challenged." (PMID 28572914, 2017).
hyperlipidemia (1 paper, 2017). "The Itga8 genotype had no influence on serum fat levels within the same Apoe genotype, and mice with a deficiency of only Itga8 (Itga8−/−) did not develop hyperlipidemia." (PMID 28572914, 2017).
ischemia (1 paper, 2025). A hypoperfusion of the BLOOD through an organ or tissue caused by a PATHOLOGIC CONSTRICTION or obstruction of its BLOOD VESSELS, or an absence of BLOOD CIRCULATION. "In light of these findings, probing the dynamic expression, distribution, and morphology of ITGA8‐expressing cells post‐ischemia is essential." (PMID 41085070, 2025). "Following MCAO, we observed a biphasic pattern of ITGA8 dynamics: vascular coverage initially decreased at days 1–3 post‐ischemia, followed by robust recovery reaching maximal levels by day 7–a timeline paralleling post‐stroke angiogenesis, indicating ITGA8 was reactivated." (PMID 41085070, 2025).
ischemic stroke (1 paper, 2025). A stroke disorder caused by obstruction of blood flow to the brain, due to thrombotic (local blood clot formation) or embolic (due to a blood clot or other material traveling from another site) event. "In an ischemic stroke model, ITGA8 deficiency results in increased BBB permeability, reduced pericyte coverage, and worsened neurological recovery." (PMID 41085070, 2025). "To address vascular dysfunction following ischemic stroke in ITGA8‐deficient mice, we investigated therapeutic ITGA8 restoration using an adeno‐associated virus vector (AAV‐PR) targeting mural cells, with pericyte‐specific transduction confirmed in Pdgfrb‐Cre; H11‐tdTomato‐GFP reporter mice." (PMID 41085070, 2025).
melanoma (1 paper, 2022). A malignant, usually aggressive tumor composed of atypical, neoplastic melanocytes. "Our analysis showed that EMT markers like N‐cadherin, ZEB1, ADAMTS9 and ITGA8, which were shown to regulate invasion in melanoma, where associated with low NRF2 target gene expression." (PMID 34951143, 2022).
neuroblastoma (1 paper, 2020). Neuroblastoma (NB) is the most common solid, extracranial childhood tumor. "Knockdown of integrin Itga8, a predicted target of miR-877-5p and -410-3p, is sufficient to convert prion-resistant neuroblastoma cells to a susceptible phenotype." (PMID 32549330, 2020).
osteoporosis (1 paper, 2025). A condition of reduced bone mass, with decreased cortical thickness and a decrease in the number and size of the trabeculae of cancellous bone (but normal chemical composition), resulting in increased fracture incidence. "Additionally, another study indicates that the subunit encoded by ITGA8 can activate Latent TGF-β, and the TGF-β signaling is highly activated in disuse osteoporosis, with inhibition of TGF-β signaling offering a potential rescue for the condition." (PMID 40130165, 2025). "Identifying 8 key genes as potential regulatory target genes for the differentiation of mesenchymal stem cells into osteoblasts or adipocytes under the condition of disuse osteoporosis (ITGB3, LAMC1, COL6A3, ITGA8, PDGFRB, ITGA4, LAMB1, LAMA4)." (PMID 40130165, 2025).
parasite infection (1 paper, 2024). "Some nodes with many edges were considered as hub genes (CD3, CD4, and ITGA8), which may play important roles in the immune response to parasite infection." (PMID 39061520, 2024).
prostate carcinoma (1 paper, 2023). A carcinoma that arises from epithelial cells of the prostate gland. "ITGA8 expression was significantly downregulated in lung, renal, rectal, and prostate cancers, suggesting that ITGA8 may be a tumor suppressor." (PMID 36911684, 2023).
skin cutaneous melanoma (1 paper, 2024). "On the other hand, according to the published literature, the level of expression of ITGA8 is considered to be closely related to metastasis in skin cutaneous melanoma and also correlated with CD8+ infiltration." (PMID 39202425, 2024).
Stroke (1 paper, 2025). Sudden impairment of blood flow to a part of the brain due to occlusion or rupture of an artery to the brain. "Conversely, adeno‐associated virus (AAV)‐mediated ITGA8 overexpression restores pericyte morphology and improveS post‐stroke neurological outcomes." (PMID 41085070, 2025). "Given the critical role of pericytes in BBB maintenance, we investigated the impact of ITGA8 deficiency on post‐stroke BBB integrity." (PMID 41085070, 2025). "Post‐stroke, days 1 and 3 see a sharp drop in ITGA8‐expressing cells on vessel walls, similar to PDGFRβ+ cells." (PMID 41085070, 2025). "By day 5, ITGA8‐expressing cells become more prominent, coinciding with more PDGFRβ+ cells on vessels, signaling the start of post‐stroke angiogenesis." (PMID 41085070, 2025). "ITGA8‐expressing pericytes emerge as key players in vascular development and in the endogenous repair response after stroke." (PMID 41085070, 2025). "In vivo, we used a transient MCAO stroke model to confirm ITGA8’s functional relevance within the full neurovascular unit." (PMID 41085070, 2025). "Our single‐cell RNA‐seq data shows that the decrease and subsequent increase in cluster 0 cells and ITGA8 expression post‐stroke align with the morphological and distribution changes of ITGA8+ cells in the brain vasculature." (PMID 41085070, 2025). "Given ITGA8’s specific post‐stroke expression and distribution, we explored ITGA8’s role in pericyte remodeling and BBB formation during post‐ischemic neovascularization." (PMID 41085070, 2025). "In post‐stroke neovascularization, ITGA8 drives pericyte remodeling and neovessel maturation, with therapeutic implications for enhancing neurovascular repair following ischemic injury and potentially mitigating neurodegenerative pathologies." (PMID 41085070, 2025). "Additionally, we isolated PDGFRβ+ brain cells from ITGA8‐Cre; H11‐GFP‐tdTomato mice on day 5 post‐stroke using fluorescence‐activated cell sorting and observed similar changing patterns of ITGA8+ cells compare to sham‐operated mice." (PMID 41085070, 2025). "An alternative approach could be gene therapy or small molecules to upregulate ITGA8 expression in pericytes during the subacute phase of stroke." (PMID 41085070, 2025). "Our investigation uncovered dynamic spatiotemporal patterns of ITGA8 expression during BBB maturation and post‐stroke vascular remodeling." (PMID 41085070, 2025). "Collectively, these findings suggest ITGA8 as a maturation‐dependent regulator of BBB integrity, with its dynamic expression profile suggesting functional involvement in both developmental barrier formation and post‐stroke vascular remodeling." (PMID 41085070, 2025).
thrombosis (1 paper, 2025). "In the current study, COL5A1, VCAN, PTGS2, ITGAV and ITGA8 were five hub genes revealed to be closed associated with thrombosis-prone plaques." (PMID 41415585, 2025). "Among them, COL5A1, VCAN, PTGS2, and ITGAV showed extremely significant increases (P < 0.01); ITGA8 was significantly decreased in the plaque group and thrombosis group (P < 0.01)." (PMID 41415585, 2025).
Ureteral obstruction (1 paper, 2016). Obstruction of the flow of urine through the ureter. "We hypothesized that the increased tubulointerstitial damage after unilateral ureteral obstruction observed in mice deficient for Itga8 is associated with altered tubulointerstitial cell turnover and apoptotic mechanisms resulting from the lack of Itga8 in cells of the tubulointerstitium." (PMID 26938996, 2016). "In contrast, unilateral ureteral obstruction in mice lacking Itga8 led to more pronounced tubulointerstitial cell activation i.e. to the appearance of more phospho-SMAD2/3-positive cells and more α-smooth muscle actin-positive cells in the tubulointerstitium." (PMID 26938996, 2016). "Thus, Itga8 seems to attenuate tubulointerstitial fibrosis in unilateral ureteral obstruction not via regulation of cell turnover, but via regulation of TGF-β signalling, fibroblast activation and/or immune cell infiltration." (PMID 26938996, 2016).
tumor (21 papers, 2017 to 2025). "We analyzed the correlation of ITGA8 and tumor mutational burden (TMB), neoantigen, and tumor heterogeneity to further explore the relationship between ITGA8 and immune microenvironment and immunotherapy." (PMID 36911684, 2023). "IKZF3 and ITGA8 were considerably more lowly expressed in the normal cell lines compared with the tumor cell lines." (PMID 36837559, 2023). "We can presume that the patients with high ITGA8 expression have lower stemness scores in the tumor, good immunotherapy efficacy, and good prognoses." (PMID 36911684, 2023). "Notably, several ligand-receptor pairs associated with tumor progression were identified between fibroblasts and immune cells, including FN1-(ITGA8+ITGB1), FN1-CD44, COL4A2-CD44, and ANGPTL1-(ITGA8+ITGB1)." (PMID 40963856, 2025). "Tumor tissues showed high expression of ITGA8 compared to normal tissues." (PMID 38755265, 2024). "Mkp-1 induces CRC metastasis by regulating the expression of the Itga8 gene, a member of the integrin family pattern recognition receptors that participate in many cellular pathways, including adhesion and metastatic spread of tumor cells." (PMID 34034704, 2021). "A starting point may be the HTICS Cell migration pathway genes (Nrp1, Npy, Cldn8) and their substitutes (Klrd1, Spink5, Itga8) identified herein—but other known markers of cancer cell dissemination or circulating tumor cells may be equally informative." (PMID 28632792, 2017). "Among these genes, ITGA8 and ADAMTS8 were downregulated in LUAD tissues and functioned as tumor suppressor genes, whereas the remaining genes were oncogenes." (PMID 35557945, 2022). "ITGA8 and ADAMTS8 were downregulated in tumor tissues, whereas FERMT1, CTSV, CPS1, ENTPD2, SERPINB5, and LYPD3 were upregulated in tumor tissues." (PMID 35557945, 2022). "The expression of ITGA4, ITGA8, ITGB2, ITGB7 and ITGB8 was correlated with the infiltration of all types immune cell and tumor purity in the SKCM TIME." (PMID 34660316, 2021). "Indeed, the top 30 significantly enriched immune modulators in ME patients included CCL8, a ligand for the tumour infiltrating Treg cells chemokine receptor CCR8, PVR, a ligand for the T cell checkpoint protein TIGIT and ITGA8, which is known to activate TGFb." (PMID 39915477, 2025). "Additionally, TENASCIN was frequently observed in the HAS group, with tumor cells in this group interacting with other cells, including tumor cells themselves, via TNC - SDC1/SDC4 or TNC - ITGA8_ITGB1/ITGAV_ITGB6." (PMID 39267750, 2024). "The results showed a negative correlation, revealing that patients with high ITGA8 expression had low tumor heterogeneity and good prognoses." (PMID 36911684, 2023). "Furthermore, ITGA8 is closely related to the immune microenvironment, TMB, tumor heterogeneity and cancer cell stemness." (PMID 36911684, 2023). "Combined with our results, we speculated that interference against ITGA8 expression could effectively increase the infiltration of CD8+ T cells in SKCM TIME and reduce the percentage of tumor cells in SKCM, which is a potential target of SKCM targeted therapy." (PMID 34660316, 2021). "Additionally, Kaplan–Meier survival analysis showed that in LUAD, patients with high ITGA8 expression were positively correlated with DSS, PFI, and OS, indicating that ITGA8 might be a tumor suppressor, and was positively correlated with good prognosis in LUAD." (PMID 36911684, 2023). "However, ITGA8 transcript was decreased in tumour tissues compared with normal tissues." (PMID 34709754, 2021).
cancer (16 papers, 2012 to 2025). A tumor composed of atypical neoplastic, often pleomorphic cells that invade other tissues. "Conversely, the inhibition of ITGA8 methylation can enhance the expression of ITGA8 mRNA, allowing a greater number of cancer cells to remain in the G0/G1 phase." (PMID 39981244, 2025). "IHC staining showed that Exo and Exo-shNC administration enhanced the expression of Ki67, a widely used proliferation marker of cancer cells, and ITGA8 in tumors, and knockdown of circTMCO3 abrogated exosome-mediated upregulation of Ki67 and ITGA8." (PMID 38755265, 2024). "We calculated cancer cell stemness scores and performed correlation analyses to investigate the relationship between ITGA8 and cancer cell stemness." (PMID 36911684, 2023). "ITGA8 was closely related to cancer stem cell (CSC), which plays an important role in immune evasion." (PMID 36911684, 2023). "To comprehensively evaluate the role of ITGA8 in multiple solid tumors, we used the TCGA dataset to examine ITGA8 expression in cancer." (PMID 36911684, 2023). "ITGA8 (integrin-alpha-8) is involved in the occurrence of several types of cancers." (PMID 36837559, 2023). "Therefore, we can speculate that ITGA8 affects cancer cell stemness through the cell adhesion and focal adhesion pathways." (PMID 36911684, 2023). "In LUAD, MethSig cancer genes with an MR/MN greater than 1, including the HOX genes PAX6 and ITGA8, were enriched for cancer progression pathways, such as motility, tissue development and morphogenesis, and transcription regulation." (PMID 40931149, 2025). "At the individual gene level, ITGA8 and ITGA9 were down-regulated in 11 out of the 15 cancers, whereas ITGAX, ITGB4, and ITGA6 were more frequently up-regulated in tumors relative to adjacent normal tissues (right)." (PMID 39436262, 2024). "These merged DMxDE datasets suggest some known or previously reported/suspected cancer genes [PR: SPARCL1, NQO1, CST1, MELK1, DPT, FAM83A, MMP9; GB: FOXM1, TFAP2, GREM1, ITGA8, GRIA1, SLIT3] as well as many previously unreported genes/loci." (PMID 26683690, 2015). "LAMA1, CHAD, ITGA8, and COL11A1 consistently showed hypermethylation in more than half of cancer types; on the contrary, TNN, SPP1, COL6A6, and TNR consistently showed hypomethylation in more than half of types of cancer." (PMID 36311789, 2022). "Furthermore, we found that some ITGs such as ITGA3, ITGA6 ITGA11, ITGB4, ITGB6, etc. were frequently upregulated in human cancers, whereas ITGs including ITGA1, ITGA7, ITGA8, ITGA9 and ITGB3, etc. were usually downregulated." (PMID 34222028, 2021).